ENSG00000252011
Gene: Small nucleolar RNA gene on chromosome 1 (246,833,448 to 246,833,529, reverse strand). Ensembl gene ENSG00000252011.
Homologues: Paralogues in human: SNORA25 (73% identical), SNORA25B (72% identical).